CDK4 (cyclin dependent kinase 4)
Diseases named in the same sentence as CDK4 in open-access papers (continued):
Sharing a sentence is not in itself a finding about the gene and the disease.
melanoma (continued). "Indeed, prior studies implied that the combination of CDK4/6 inhibition and BRAFi halted the cell growth of several melanoma lines in vitro and in vivo." (PMID 32413516, 2020). "However, few mutations were identified in the reported melanoma-susceptibility genes CDKN2A and CDK4." (PMID 32083130, 2020). "To investigate whether CDK4 or CDK6 are also involved in cell migration in melanoma we performed scratch assays with the 518A2 and LNM1 stable shRNA clones." (PMID 30858922, 2019). "Recent studies showed sensitivity of human melanoma cell lines for CDK4/6 inhibitor treatment." (PMID 30858922, 2019). "Melanoma cells are sensitive to CDK4/6 inhibitors in vitro and in vivo." (PMID 30858922, 2019). "Furthermore, the expression levels of CCNA2, CCNB1, CDK1, and CDK4 decreased in melanoma cells treated with metformin, whereas the levels of p21 and CCND1 increased." (PMID 30754729, 2019). "Drug sensitivity tests showed that AT7519, a broad-spectrum CDK inhibitor, and PD0332991, a specific CDK4/6 inhibitor, exhibited higher inhibitory effect on CDK4 signaling pathway abnormal mucosal melanoma cells-derived PDX tumors growth than CDK4 signaling pathway normal ones." (PMID 31358010, 2019). "The results so far suggest that pro-angiogenic effects are not only mediated by CDK6 in melanoma but that CDK4 may also be involved." (PMID 30858922, 2019). "As mutations in high-susceptibility genes greatly increase risk of melanoma development, individuals carrying CDKN2A, CDK4, BAP1, POT1, or MITF mutations should be educated on the importance of melanoma prevention and early detection and should undergo regular medical skin examination." (PMID 31717496, 2019). "Thus, our data provide the foundation to investigate the presence and loss of pRb-Ser780 as a biomarker of acquired resistance to BRAF/MEK inhibition and a biomarker of response to BRAF/MEK/CDK4/6 therapy in BRAFV600E-mutant melanomas, respectively." (PMID 29541385, 2018). "We also showed that CDK4/6 blockade resensitized drug resistant melanoma to SOC therapy." (PMID 29541385, 2018). "CDKN2A/CDK4 were the first high- penetrance melanoma genes identified." (PMID 29774366, 2018). "The CDK4 gene is often amplified and overexpressed in a variety of cancers including melanoma." (PMID 28788083, 2017). "Recently, alternative experimental approaches have been identified to inhibit NRAS-mutated melanomas: particularly, it was shown in experimental models of NRAS-mutated melanomas that the combined inhibition of MEK and CDK4 induced apoptosis and inhibited tumor cell proliferation." (PMID 29156643, 2017). "Conversely, cell cycle genes as CDKN2A and CDK4 have been excluded as predisposing for melanoma in MeLiM." (PMID 29081790, 2017). "Norway has among the highest incidences in the world of malignant melanoma with an accumulated risk up to the age of 75 of 2.4 % for both genders, while mutations in CDKN2A and CDK4 were only found in 6.9 % in a population-based study among individuals with multiple primary melanomas (MPM)." (PMID 27804060, 2017). "Although p16 may interact with both CDK4 and CDK6, p16 inhibition of CDK4 may be more important than CDK6 given that some melanoma-prone families have inherited activating mutations in CDK4, while none with activating CDK6 mutations have been described." (PMID 28915557, 2017). "Samples affinity-purified for melanoma-associated mutant versions of CDK4 showed increases in HSP90 abundance, suggesting that these mutants associate more or form a stronger association than wild-type CDK4 with HSP90." (PMID 27092249, 2016).
melanoma (continued). "Our results also highlight the importance of the Wnt/β-catenin and their transcriptional targets (including c-myc, survivin, cyclin D1, CDK4, and MMPs), which may serve as future targets for the development of therapeutic strategies against human melanoma." (PMID 26968952, 2016). "Second, RAS-mutant melanoma and CRC have markedly different patterns of concomitant genomic alterations, such as CDKN2A loss, which are likely to be associated with sensitivity to CDK4/6 inhibitors." (PMID 27167191, 2016). "The UK family with the promoter variant was identified came from a series of 139 three-or-more case melanoma families, of which 56 (40 %) have a CDKN2A mutation; 2 (1.4 %) have a CDK4 mutation, 4 (2.8 %) have shelterin mutations, and now 1 (0.7 %) has a TERT promoter mutation." (PMID 26433962, 2016). "Two high-risk genes associated with melanoma have been identified so far: CDKN2A and CDK4." (PMID 27022491, 2016). "In addition, CDK4/6 kinases have been proposed as promising pharmacological targets in BRAF inhibitor-resistant melanoma." (PMID 26295265, 2015). "CDK4 protein was detected at high levels in the panel of 8 melanoma cell lines." (PMID 26201960, 2015). "Fascaplysin, a synthetic CDK4 inhibitor, was further tested in 8 melanoma cell lines." (PMID 26201960, 2015). "Other high-risk melanoma genes have been discovered: cyclin-dependent kinase 4 (CDK4), BRCA-1 associated protein (BAP1), and recently via exome sequencing of dense melanoma families, several new high-risk genes affecting telomere functions have been identified: POT1, ACD, TERF2IP and TERT." (PMID 25803691, 2015). "In addition, activity of CDK4/6 is frequently up-regulated by deletion of CDKN2A (p16INK4a) or increased expression of cyclin D1 in melanoma." (PMID 26295265, 2015). "These factors provide evidence that CDK4 plays an important role in melanoma progression." (PMID 26201960, 2015). "In summary, targeting CDK4 inhibits growth and induces apoptosis in melanoma cells in vitro, suggesting that CDK4 may be a rational therapeutic target for metastatic melanoma." (PMID 26201960, 2015). "Interestingly, the combination of inhibitors against the MEK1 and CDK4/6 pathways was synergistic in an inducible NRASQ61K-driven mouse model of melanoma and showed striking in vivo tumor regression." (PMID 25162504, 2014). "In the case of familial melanoma, germline inactivating mutations in the CDKN2A/B locus (mainly p16 and p14) are common, leading to aberrant CDK4/cyclin D activity that drives melanoma cell cycle progression." (PMID 23750336, 2013). "Mouse models show that the CDK4R24C form enhances melanoma penetrance in cooperation with the oncogenic HRasG12V, which is found in the subset of atypical spitzoid melanomas or after specific carcinogenic treatments, thereby supporting the notion that CDK4 is important for melanoma development." (PMID 24416617, 2013). "For example MGHU1 human bladder cancer and G361 human melanoma cells both exhibited total cell death with the same dose of 200 μM THR53 but respectively had markedly different endogenous Cdk4 values of 3.605 ± 0.735 and 6.035 ± 1.765 and Cyclin D1 values of 3.465 ± 0.832 and 1.055 ± 0.292." (PMID 21668989, 2011). "Additionally, a substitution of Cysteine for Arginine at the 24th codon of CDK4 is observed in a small percentage of melanoma-prone families." (PMID 21479172, 2011). "In some melanomas, BRAF mutations occur along with other mutations in genes such as PTEN and CDK4." (PMID 21479172, 2011). "Absence of mutations at the CDKN2A or CDK4 loci, even in families with very large numbers of melanoma cases therefore indicate other yet to be identified high penetrance susceptibility genes." (PMID 24281082, 2010).
melanoma (continued). "The present study has shown high prevalence of p16INK4A mutations in Slovenian population of familial melanoma patients (37%) and an absence of p14ARF or CDK4 mutations." (PMID 18803811, 2008). "The present study has shown a high prevalence of CDKN2A mutations affecting p16INK4A in Slovenian population of familial melanoma patients (37%) and an absence of p14ARF or CDK4 mutations." (PMID 18803811, 2008). "Among the 214 melanoma-prone families recruited through the French Familial Melanoma Project, 46 families were positive for point mutations within CDKN2A (21.5%), one family carried a CDK4 point mutation in exon 2 (0.5%), and one family carried a large CDKN2A deletion (0.5%)." (PMID 18612309, 2008). "Two highly penetrant melanoma-predisposing genes have been identified to date, INK4a-ARF and Cdk4." (PMID 14735200, 2004). "To investigate more precisely the role of genetic mechanisms in the aetiology of melanoma, we performed a mutational analysis of INK4a-ARF and Cdk4 genes (exon 2) and a deletion analysis of INK4a-ARF in a series of 89 cases of melanoma with suspected hereditary predisposition." (PMID 14735200, 2004). "We hypothesized that germline mutations in the p16INK4A, p14ARFor CDK4 genes might contribute to some cases of familial UMM, or to some cases of UMM associated with another melanoma." (PMID 10732752, 2000). "Furthermore, CDK4 gene amplification is also found in melanomas, sarcomas, and glioblastomas." (PMID 38275873, 2024). "No CDK4 pathogenic variants have been identified in Brazilian melanoma-prone families to date." (PMID 35085295, 2022). "However, in addition to these favorable effects, continuous co-treatment with BRAFi, MEKi and CDK4/6i potently depletes melanoma tumors of myeloid cells, including immune-potentiating subsets, such as chemokine-producing macrophages and cross-priming CD103+ DCs18." (PMID 35444175, 2022). "Additionally, the potential therapeutic value of MEK inhibitors combined with inhibition of downstream effectors (MAPK, PI3K, or CDK4/6) or upstream effectors (RTK, STK19) for melanomas with NRAS mutations has been demonstrated, but the choice remains controversial." (PMID 36125617, 2022). "The gene p16 may also potentially be involved in the occurrence of these malignancies since it inhibits the cyclin‐dependent kinase CDK4 (CD4 K and CDKN2A being known melanoma susceptibility genes) and since some mutations of p16 were reported in different types of lymphoma." (PMID 33219744, 2021). "Furthermore, we demonstrated the sensitivity of three oral melanoma cell lines, including a metastatic one, to treatment with a CDK4/6 inhibitor, suggesting this could be a new effective therapeutic approach for canine oral melanoma." (PMID 34485433, 2021). "Notably, it seems that NRAS-mutant melanoma could be particularly sensitive to the combined CDK4/6/BRAF/MEK inhibition." (PMID 34071228, 2021). "Furthermore, CDK4 overexpression has been observed in uterine cervical and colorectal carcinomas, melanomas, as well as NSCLC, while CDK4 gene amplification has occurred in glioblastomas, uterine cervix cancer, osteosarcomas, rhabdomyosarcomas, and liposarcomas." (PMID 34361615, 2021). "Additionally, the combination of CDK4 and MAPK pathway inhibitors has shown tumor regression in xenograft models of cancers with KRAS, NRAS, or BRAF mutations, particularly BRAF- and NRAS-mutant melanoma, with promising results from phase I clinical studies." (PMID 34309585, 2021).
melanoma (continued). "We observed that H2AFZ and MCM2 were expressed at relatively high levels in CMM12 melanoma cells compared to the other cell lines, suggesting a possible utility of E2F target gene expression in tumor cells as markers to predict response to treatment with a CDK4/6 inhibitor." (PMID 34485433, 2021). "Preclinical studies in melanoma, glioblastoma, and ovarian cancer have shown that low levels of p16 and the high expression of cyclin D/Retinoblastoma (Rb) proteins may be thought as biomarkers for the prediction of sensitivity to the CDK4/6i." (PMID 33923563, 2021). "However, their study has already highlighted palbociclib as a possible agent in treating ALM patients with aberrations in the CDK4 pathway, which highlights the power of these kinds of preclinical studies and calls for more research for this subtype of melanoma." (PMID 32330367, 2021). "Moreover, the addition of cyclin dependent kinase 4/6 inhibitors (CDK4/6i) have been shown to greatly extend duration of response in combination with BRAF-MEK inhibitors (BRAF-MEKi) in pre-clinical models of melanoma." (PMID 34944961, 2021). "Notably, XL888 efficiently exerted similar effects in three-dimensional spheroid cultures, and in a mouse xenograft model of melanoma with milder effect on the activity of MAPK signaling pathway but retaining its inhibitory potential on CDK4 and WEE1 expression, and activity of AKT and S6." (PMID 31659567, 2020). "We therefore applied our platform to quantify how pMHC repertoires in melanoma change in vitro upon treatment with the CDK4/6 inhibitor, palbociclib, to better understand how CDK4/6 inhibitors could be leveraged in combination therapy regimes to improve patient outcomes." (PMID 32488085, 2020). "Furthermore, hereditary melanoma has been associated with germline mutations in high-risk melanoma susceptibility genes (CDKN2A, CDK4, TERT, POT1), polymorphisms in intermediate-risk melanoma susceptibility genes (BAP1, ACD, TERF2IP, MC1R and MITF), and germline missense substitutions in MITF." (PMID 32276436, 2020). "However, drug resistance to CDK4/6 inhibitors occurred in melanoma treatment." (PMID 32859239, 2020). "Thus we set out to determine whether depletion of neutrophil infiltration using a neutrophil-blocking anti-Ly6g antibody would influence subsequent melanoma induction in Cdk4::NRAS mice." (PMID 30681412, 2019). "Although the underlying genetic basis in the majority of melanoma-prone families is unknown, certain highly penetrant genes, such as the cyclin-dependent kinase inhibitor 2A (CDKN2A) gene and cyclin-dependent kinase 4 (CDK4), have been implicated." (PMID 29774366, 2018). "However, our clinically relevant preclinical PDTX mouse models confirm and support the conclusion that BRAF/MEK inhibitors combined with CDK4/6 inhibitors effectively inhibits tumor growth in BRAFV600E-mutant melanomas by simultaneous or subsequent targeting of the cell cycle machinery." (PMID 29541385, 2018). "In summary, CDK4 inhibitor palbociclib may be a strong inhibitor of melanoma cell proliferation in the absence of BRAF and NRAS mutations in melanomas with homogeneous CDK4 expression." (PMID 27903987, 2017). "Importantly, loss‐of‐function mutations in CDKN2A, and its binding partner, the product of the cyclin‐dependent kinase 4 (CDK4) gene, have been identified in highly melanoma‐prone families 8, 9, 10, firmly linking disruption of cell cycle control and melanoma risk." (PMID 26354726, 2016). "The lower sensitivity in the primary WM-115 cells, suggests that primary melanomas might be less sensitive to CDK4 inhibition than metastatic tumours but this would require further testing in a larger panel of cell lines derived from primary and metastatic tumours." (PMID 26201960, 2015).
melanoma (continued). "Furthermore, mutation or overexpression of CDK4, combined with amplification of cyclin D1, has been implicated in resistance to BRAF inhibition in V600E-mutated melanoma cells, and amplification of cyclin D1 is detected in ~17% of BRAF V600E-mutated human metastatic melanomas." (PMID 26201960, 2015). "The first clues about the molecular basis of melanoma came from studies of families prone to the disease and the identification of two autosomal-dominant high-susceptibility loci: cyclin-dependent kinase inhibitor 2A (CDKN2A) and cyclin-dependent kinase 4 (CDK4)." (PMID 22339359, 2012). "A positive family history is a strongly associated risk factor for melanoma, and approximately 50% of affected families have mutations in one of the three following genes: cyclin-dependent kinase inhibitor 2A (CDKN2A), alternate reading frame (ARF), and cyclin-dependent kinase 4 (CDK4)." (PMID 21203498, 2010). "Moreover, we obtained evidence that no sequence variation was present in p15CDKN2B and CDK4, the remaining two high penetrance melanoma susceptibility genes, among familial melanoma cases from our southern Italian population (and unpublished data)." (PMID 19799798, 2009). "No germline mutation of Cdk4 exon 2 was detected in any melanoma patient." (PMID 14735200, 2004). "To evaluate the effects of CDK4/6 and CDK2 inhibitors on the cell cycle of B16F10 and 1014 melanoma cells, we chose a 24-hour treatment time to ensure capture of early and drug-specific effects." (PMID 40904502, 2025). "They showed that treatment of cells with both drugs reduce the expression levels of cyclin D1, CDK4 and CDK6 in melanoma cells, and their results are consistent with those of our study." (PMID 41373567, 2025). "In a recent study a researcher performed single-cell RNA sequencing on NRAS-mutant melanomas treated with MEK1/2 and CDK4/6 inhibitors to decode the transcriptional transitions occurring during the development of drug resistance." (PMID 40872623, 2025). "In prior studies, CDK4/6 inhibitors resulted in disease control rates (DCR) of 49% (n = 68) and 44% (n = 18) in non-small cell lung cancer and melanoma patients, respectively." (PMID 41271634, 2025). "In 1014 melanoma cells, even with high-dose CDK2 inhibition, addition of the CDK4/6 inhibitor was required to suppress cyclin E1 levels." (PMID 40904502, 2025). "Overexpression of FOXF1 adjacent non-coding developmental regulatory RNA (FENDRR) reduces cyclin E1, cyclin D1, CDK4, and CDK6 levels, which arrests melanoma cells in the G1 phase." (PMID 41463281, 2025). "The dual inhibition of CDK4/6 (palbociclib) and PRMT5 (GSK3326595) more effectively suppressed tumor growth than palbociclib alone in melanoma models with acquired resistance to palbociclib." (PMID 40282469, 2025). "We have previously demonstrated that combined treatment with a CDK4/6 inhibitor and an MDM2 inhibitor suppresses the growth of melanoma patient-derived xenografts and that knockdown of CDK2 overcomes resistance to CDK4/6 inhibition." (PMID 40904502, 2025). "Here, we initiate a preclinical study using murine BRAFWT murine B16-F10 melanoma and NRASmut 1014 melanoma cells to examine the effectiveness of combining the CXCR1/2 antagonist, SX-682, with the CDK4/6 inhibitor, palbociclib." (PMID 40904502, 2025). "Of the nine putative proteomic biomarkers studied in an independent cohort using IHC, CDK4, ADAM10, SCAI, and DDX11 seem promising starting points for further investigation of their role in melanoma routine diagnostics." (PMID 40075679, 2025). "The genes CDKN2A/B and CDK4 (also referred to as CDK genes), frequently altered in malignant melanoma, play a critical role in tumor development and progression." (PMID 38982214, 2024). "As dysregulations in the RB pathway are frequently observed in UM (about 90% of all cases), recent studies focus on targeting CDK4 and CDK6 in this melanoma subtype." (PMID 39598629, 2024).